S100A16 (S100 calcium binding protein A16)
Diseases named in the same sentence as S100A16 in open-access papers (continued):
Sharing a sentence is not in itself a finding about the gene and the disease.
cancer (45 papers, 2013 to 2026). A tumor composed of atypical neoplastic, often pleomorphic cells that invade other tissues. "For instance, in the context of cancer, altered S100A16 expression has been associated with tumor development, progression, and metastasis in certain cancer types." (PMID 38710691, 2024). "Univariate analysis showed that S100A16 expression was significantly associated with age, pT stage, recurrence, and cancer-specific death." (PMID 37833982, 2023). "Age at cystectomy, pT stage, recurrence, and cancer-specific death were associated with S100A16 expression." (PMID 37833982, 2023). "Currently, little is known about S100A16; and almost all publications focus on its association with cancer." (PMID 35061207, 2022). "Notably, S100A16 has been implicated in various disease processes, including cancer, inflammation, metabolic disorders, and kidney diseases." (PMID 38710691, 2024). "We report here for the first time that S100A14 and S100A16, which have been previously shown to be associated with cancer cell invasion, are abundant in blastocysts and appear to be localized to the trophectoderm, consistent with a role in the invasiveness of the trophoblast during implantation." (PMID 27241529, 2016). "We next examined whether S100A16 over-expression is also associated with the concomitant change in the expression of S100A14 in cancer cell-lines." (PMID 24086685, 2013). "Multiple studies have identified EMT as the lynchpin by which S100A16 influences many attributes of cancer progression, such as proliferation, migration, and drug resistance." (PMID 40846689, 2025). "S100A16 is widely expressed in various tissues, including the brain, lungs, kidneys, and adipose tissue; yet its expression is often dysregulated in cancer and other diseases." (PMID 40846689, 2025). "In line with our findings, S100A16 has been previously reported as a potential biomarker, a correlate of poor prognosis, and a driver of metastasis in a variety of cancers." (PMID 40846689, 2025). "S100A16 expression is dysregulated in various human cancers, confirming its role in tumor development and metastasis." (PMID 40846689, 2025). "S100A16, part of the expansive S100A family, emerges as a key player in cancer biology, exhibiting diverse functions in tumorigenesis." (PMID 38520747, 2024). "In recent years, more and more studies have focused on the role of S100A16 in tumorigenesis and cancer metastasis." (PMID 38271114, 2024). "Compared to normal tissues, the mRNA and protein levels of S100A16 have been reported to be differentially expressed in several cancer types." (PMID 37509106, 2023). "Accordingly, S100A16 has been suggested to have both tumour-promoting and suppressive roles in human cancers." (PMID 37509106, 2023). "By analyzing the relationship between S100A16 and the subsequent immune response within the TCGA datasets we probed the potential cancer progression molecular mechanisms influenced by S100A16." (PMID 37978469, 2023). "In order to indicated the role of the family members in HCC development, we further analyzed the expression of S100A4, S100A6, S100A10, S100A11 and S100A16 in pan-cancer, and the results suggested that they were highly expressed in most tumors." (PMID 37420211, 2023). "S100A16 expression was significantly correlated with age, pT stage, recurrence, and cancer-specific death." (PMID 37833982, 2023). "The aims of this review are to summarise the expression profile, identify common molecular partners and functional roles, and explore the prognostic potential of S100A16 in human cancers." (PMID 37509106, 2023). "mRNA and protein levels of S100A16 have been reported to be differentially expressed in the majority of human cancers." (PMID 37509106, 2023). "Kaplan–Meier analyses showed that patients with S100A16 expression had shorter overall survival (OS), cancer-specific survival (CSS), and recurrence-free survival (RFS) than those without S100A16 expression." (PMID 37833982, 2023).
cancer (continued). "Tomiyama N. and co-workers investigated the role of S100A16 in cancer stem cells using Yumoto cells (a CC cell line)." (PMID 37509106, 2023). "Expression of S100A16 was altered in several human malignancies, indicating a possible role for S100A16 in cancer." (PMID 37509106, 2023). "In our study, the lower level of S100A16 transcript observed in the HPNE control cell line compared to the eight cancer cell lines, is in agreement with the Oncomine data analysis." (PMID 37627239, 2023). "Previous studies have reported high expression of S100A16 in malignant tumors and the promotion of cell invasion and tumor development." (PMID 35279748, 2022). "Recent research has indicated that the calcium-binding protein S100A16 promotes carcinogenesis and tumor growth in several forms of cancer." (PMID 36176934, 2022). "According to the Oncomine database query, the analysis of cancer and all normal comparisons, contains 265 different scientific studies on S100A16." (PMID 33912559, 2021). "It has been widely reported before that S100A16 is upregulated in various types of cancer cells in the comparison with the normal tissues." (PMID 34650982, 2021). "Recent studies have shown that MYEOV, KCNN4, and S100A16 act as oncogenes and play vital roles in cancer progression." (PMID 34789165, 2021). "Quantitative RT-PCR (1.33 ± 0.77 vs. 1.10 ± 0.69, p = 0.038) and IHC (8.89 ± 2.93 vs. 7.08 ± 3.02, p = 0.023) showed that S100A16 expression was higher in cancer than in adjacent normal tissues." (PMID 33921267, 2021). "The S100A16 was also upregulated in various types of cancer, including bladder, lung, and pancreatic." (PMID 31877708, 2019). "The highest up-regulated lncRNA was lnc-MMP10-3 (absolute FC = 1469.95) among ESCC tissues versus paired non-carcinoma tissues and a total of 809 genes (e.g. S100A16, OLFML2B, and CAST) were related to lnc-MMP10-3 as the standard of absolute PCCs value > 0.8." (PMID 31235759, 2019). "By comparing S100A16 expression using the RNA-Seq data, we found that the cancer tissues had significantly elevated S100A16 expression compared with the normal lung tissues (N = 59)." (PMID 29746588, 2018). "Of these 20 paired samples, 14 showed significantly higher S100A16 mRNA expression in the cancer tissue compared with the adjacent tissue." (PMID 25287362, 2014). "In this study, we show that S100A14 interacts with another S100 protein, the S100A16, and modulates its expression in human cancer cell lines." (PMID 24086685, 2013). "Similar to S100A14, recent studies have shown differential expression of S100A16 in different human malignancies, suggesting a role of this protein in human cancers." (PMID 24086685, 2013). "The biological significance of the interaction between S100A14 and S100A16 was next examined by over-expressing S100A14 in a number of human cancer cell-lines (CaLH3, VB6, H357, OSCC1 and HeLa) using a retroviral mediated gene expression strategy." (PMID 24086685, 2013). "As the fold change threshold increased (>3.0), the number of differentially expressed genes decreased, but core regulatory genes such as ADGRL2, NR2F1, S100A16, and KRT19 remained consistently altered, highlighting isoform-specific regulation of key cancer-associated genes." (PMID 41300774, 2025). "Thus, brain endothelial cell-derived extracellular vesicles contribute to SCLC brain metastasis by upregulating S100A16 and enhancing cancer cell survival." (PMID 40846689, 2025). "The prognostic risk model based on six DMGs in our study, namely FAM83A, S100A16, E2F7, ANLN, C1QTNF6 and GAPDH, suggests that they might reveal causes of the cancer development and tumorigenesis in LUAD." (PMID 38711158, 2024). "There are some studies showing that S100A16 induces EMT in several cancer types." (PMID 37833982, 2023).
cancer (continued). "The differential expression pattern of S100A16 and its involvement in key signalling pathways regulating various cellular functions in human cancers suggest that S100A16 might be a promising prognostic marker and a therapeutic target in human cancers." (PMID 37509106, 2023). "We further analyzed the expression of S100A16 in cancer tissues and adjacent normal tissues." (PMID 33921267, 2021). "Importantly, S100A16 is a ubiquitously expressed protein, which is up-regulated in various malignant tumors." (PMID 25287362, 2014). "However, the physiological and pathological roles of S100A16, especially its roles in cancer, are largely unknown." (PMID 25884418, 2015). "However, the physiological functions of S100A16 in malignant tumors are still undefined." (PMID 25287362, 2014). "Indeed, over-expression and knock-down of S100A14 in several cancer cell-lines was associated with concomitant up- and down-regulation of S100A16 protein but not mRNA." (PMID 24086685, 2013). "Due to the overexpression of S100A16 in PDAC and its role in promoting cancer progression through FGF19-mediated signaling pathways, S100A16, as well as the potentially involved FGF19 signaling pathways, are considered promising therapeutic targets for PDAC." (PMID 41328353, 2026). "Critically, reduced S100A16 expression mitigated the SPDEF overexpression-induced enhancement of PAAD cell proliferation, underscoring its influence on cancer cell dynamics." (PMID 38520747, 2024). "In this study, we analyzed S100A16 expression with the GEPIA database and the UALCAN cancer database." (PMID 34650982, 2021). "The data showed that S100A4, S100A14 and S100A16 were significantly higher in PDAC tissues compared with their counterparts, but the protein level of S100A2, S100A6 and S100A10 were similar between cancer tissues and their counterparts." (PMID 34530774, 2021). "To analyze the functional roles of S100A14 and S100A16 in cancer cells, we examined the cellular behavior of MCF7 and SK-BR-3 cells transfected with S100A14 and S100A16 specific siRNAs." (PMID 25884418, 2015). "Furthermore, S100A16 is prominently expressed in PDAC and is crucial in promoting the proliferation, migration, and invasion of these cancer cells, with its effects being dependent on FGF19." (PMID 41328353, 2026). "Additionally, the potential interplay between SPDEF, S100A16, and the PI3K/AKT signaling pathway is of considerable interest given the significance of this pathway in various cancers." (PMID 38520747, 2024). "Further, over-expression of S100A14 was found to increase the S100A16 protein level but not the mRNA expression levels in the human cancer cell lines studied, indicating a role for S100A14 in possible post-transcriptional regulation of the S100A16 protein." (PMID 37509106, 2023). "Genes with no significant expression in the majority of the normal donors and exhibiting expression patterns associated with a particular cancer type were 16, among them AGR2, S100A14, S100A16, and FABP1 identified as those with the highest discrimination power between cases with cancers and donors." (PMID 36428760, 2022). "Previously, MYEOV, KCNN4, S100A16, and FAM83A had been reported as oncogenes in various types of cancer, which could promote the proliferation and invasion of cancer cells." (PMID 34789165, 2021). "We have focused on the detection of novel biomarkers of cancer progression including of invasion and metastasis based on experimental studies and have identified the S100 family proteins S100A14 and S100A16 as important candidate molecules for the regulation of metastatic disease." (PMID 25884418, 2015). "Given the high probability of chromosomal rearrangement in 1q21 region (where S100A16 is located) in human cancers, one of the mechanisms for S100A16 down-regulation in OSCC could be the deletion of S100A16 locus in these lesions." (PMID 26353754, 2015).
cancer (continued). "Altered expression of S100A16 has been reported in human cancers, but its biological role in tumorigenesis is not fully understood." (PMID 26353754, 2015). "There have been many reports of S100A14 expression in a variety of cancers, whereas S100A16 has not been well analyzed in clinical cases." (PMID 25884418, 2015). "Hence, it will be a future challenge to examine how S100A14 is involved in the regulation of S100A16 expression and to understand the functional significance of S100A14/A16 heterodimer in normal and the cancer cells." (PMID 24086685, 2013). "In contrary, no appreciable effect was observed both on the mRNA and the protein levels of S100A14 when S100A16 was over-expressed in cancer cell-lines, suggesting a unidirectional regulation between S100A14 and S100A16 where only S100A14 regulates protein abundance of S100A16." (PMID 24086685, 2013). "Having observed an increase only in the S100A16 protein and not in S100A16 mRNA expression when S100A14 was over-expressed in the cancer cells, we speculated that S100A14 might be involved in the regulation of S100A16 protein degradation." (PMID 24086685, 2013). "However, there was no increase in the mRNA expression levels of S100A16 in these S100A14 over-expressing cancer cell-lines." (PMID 24086685, 2013).
tumor (41 papers, 2015 to 2026). "Several studies have shown that abnormal expression of the S100A16 gene is associated with tumor progression and prognosis." (PMID 40481236, 2025). "We next sought to determine the metastatic potential of these tumors given that the overall impedance on tumor growth was modest with the loss of S100A16." (PMID 40846689, 2025). "The loss of S100A16 at the tumour-invading front was found to be associated with poor tumour differentiation and reduced patient survival." (PMID 37509106, 2023). "Analysis of publicly available transcriptomic datasets has further indicated a possible association between S100A16 and immune infiltrates in the tumour microenvironment." (PMID 37509106, 2023). "As a member of the S100 protein family,Studies have shown that S100A16 overexpression was associated with varying tumor occurrence and progression rates." (PMID 37978469, 2023). "We examined the specific signaling pathways associated with S100A16 to explore the underlying molecular mechanisms by which S100A16 influenced tumor progression." (PMID 37978469, 2023). "Further, studies have reported that low immunoexpression of S100A16 was found to be associated with an aggressive tumour phenotype and poor patient survival, as compared to patients with high expression." (PMID 37509106, 2023). "Higher expression of S100A16 was reported to be associated with larger tumour sizes, the presence of lymph node metastasis, and poor patient survival." (PMID 37509106, 2023). "S100A14 is a prominent ligand of RAGE signaling pathways, and S100A16 is the most associated protein, implying that S100A16 has a role in tumor invasion and development." (PMID 36613714, 2022). "High expression of S100A16 was associated with worse overall survival, tumor stage, high TP 53 mutation, and drug resistance." (PMID 34804125, 2021). "S100A16 expression was positively correlated with H. pylori infection (a recognized GC pathogenic factor), as well as with the tumor grade of GC." (PMID 34650982, 2021). "In addition, bioinformatics analyses and in vitro tests were conducted to study the influence of S100A16 on the behaviour and underlying processes of tumor cells." (PMID 36176934, 2022). "Firstly, significantly reduced S100A16 expression at the invading front/island as compared to the tumor center and, severely down-regulated expression in the positive lymph nodes indicated that loss of S100A16 might be necessary for the tumor cells to acquire an invasive phenotype." (PMID 26353754, 2015). "At 5 days post injection S100A16 silenced tumors were noticeably smaller than those of the vector control cells; however, minimal differences were seen until 21 days when tumor growth was blunted as compared to controls." (PMID 40846689, 2025). "We find that S100A16 expression corresponds with mammary gland developmental stages that mirror key aspects of tumor progression and metastasis." (PMID 40846689, 2025). "In our analysis, both KRT8 and S100A16 were upregulated in LUAD tumor tissues, reinforcing their roles in LUAD progression and highlighting their potential as immune-related therapeutic targets." (PMID 41239716, 2025). "MCF10CA cells silenced for S100A16 were injected into the fat pads of nude mice and tumor growth was monitored over the course of three weeks." (PMID 40846689, 2025). "According to the studies, we found that the upregulation of CRISP3, S100A13, and S100A16 in domain 3 suggests that this region possesses tumor invasiveness, metastatic potential, and an active inflammatory environment, thereby promoting tumor progression." (PMID 41223185, 2025). "Elevated expression of S100A16 in the tumor microenvironment promotes the formation of tumor-related blood vessels, facilitating tumor growth." (PMID 39513103, 2024). "S100A16 mRNA level was significantly increased in PC tumour tissues when compared to normal tissues." (PMID 38924205, 2024).